CAPN10 (calpain 10)
Diseases named in the same sentence as CAPN10 in open-access papers (continued):
Sharing a sentence is not in itself a finding about the gene and the disease.
Insulin resistance (16 papers, 2008 to 2024). Increased resistance towards insulin, that is, diminished effectiveness of insulin in reducing blood glucose levels. "TCF7L2 has been strongly linked to elevated HbA1c levels and an increased risk of T2D, FTO rs9939609 variant has been linked to high HbA1c levels and insulin resistance, and CAPN10 has been associated with insulin resistance and T2D." (PMID 39275336, 2024). "Multiple polymorphisms in CAPN10 gene individually or in combination were demonstrated to regulate gene expression and be associated with insulin resistance and PCOS." (PMID 37727373, 2023). "Diabetic patients showed decreased calpain-10 expression in the pancreas and skeletal muscle, which was associated with insulin resistance." (PMID 34440550, 2021). "Several case control and association studies indicated that polymorphisms in CAPN10 are associated with the development of T2D and insulin resistance, more so in obese patients with an earlier age of disease onset." (PMID 20470430, 2010). "Our results suggest that CAPN10 gene is associated with insulin resistance phenotypes in the Spanish population." (PMID 18698425, 2008). "Our main outcome is the identification of association between CAPN10 gene variants and two estimators of insulin resistance: the glucose levels after an oral glucose tolerance test (OGTT) and the HOMA index." (PMID 18698425, 2008). "Researchers hypothesized that CAPN10 gene polymorphisms may contribute to the development of PCOS because that insulin resistance was considered as the common pathologic basis of T2DM and PCOS." (PMID 37727373, 2023). "Risk alleles like FTO, ADIPOQ, INSR, IRS1, IRS2, PPARG, CAPN10 may leave individuals more vulnerable to insulin resistance and/or adiposity (which can result in peripheral insulin resistance), leading to high circulating insulin." (PMID 31367382, 2019). "In this way, the CAPN5 homologue, CAPN10, has been shown to exist within the mitochondria and to be involved in pancreatic β-cell apoptosis, a process postulated to underlie the association of this gene with the insulin resistance phenotype." (PMID 18657264, 2008). "However, whether the mechanisms underlying the role of CAPN2 in insulin resistance are identical to those of CAPN10 warrants further in-depth investigation." (PMID 38610028, 2024). "Our research introduces the concept of a significant correlation between CAPN2 and insulin resistance, akin to that observed with CAPN10." (PMID 38610028, 2024). "By identifying CAPN2, our research contributes to the expanding evidence surrounding the CAPN family, particularly CAPN10, in insulin resistance studies beyond PCOS." (PMID 38610028, 2024). "Several case–control and association studies have indicated that polymorphisms in CAPN10 are associated with the development of T2DM and insulin resistance." (PMID 38139275, 2023). "While UCSNP-43 alone has been strongly associated with T2DM and insulin resistance, both UCSNP-43 and -44 have been implicated in the transcriptional regulation of the CAPN10 gene." (PMID 22384174, 2012). "Gene variants related to insulin resistance such as insulin gene (VNTR), insulin receptor (INSR), insulin receptor substrate proteins (IRS1/2) and calpain-10 have shown to be associated with PCOS and related metabolic abnormality." (PMID 21492415, 2011). "Within this gene family, CAPN10 has emerged as a novel factor in insulin resistance." (PMID 38610028, 2024). "However, distinct meta-analyses and also functional studies have confirmed the role of CAPN10 in insulin resistance phenotypes." (PMID 18698425, 2008). "Furthermore, Western blot analyses of adipose tissue from either 5 or 16 weeks LFD and HFD mice showed no alterations in protein abundance of calpain-10, an atypical calpain associated with insulin resistance in diabetic populations (Figure SIIIE,F in the online-only Data Supplement)." (PMID 29089532, 2017).
Obesity (10 papers, 2010 to 2026). Accumulation of substantial excess body fat. "The Calpain 10 genes (CAPN10) have been originally identified through linkage studies associated with T2DM and obesity; variants were associated to subclinical atherosclerosis and factors determining a pre-diabetic phenotype in a non-diabetic Mexican-American population." (PMID 24892324, 2013). "Nuclear genes, including calpain 10 (CAPN10), cytochrome family P450, insulin (INS) gene, androgen receptor (AR), fat mass obesity (FTO) gene, and follicle-stimulating hormone receptor (FSHR) gene, have been shown to be associated with PCOS." (PMID 37674615, 2023).
polycystic ovary syndrome (5 papers, 2007 to 2023). A disorder that manifests as multiple cysts on the ovaries. "In this way, other insulin related disorders have been linked to CAPN10 gene such as polycystic ovary syndrome (PCOS)." (PMID 18698425, 2008). "We present here the results of our pioneering effort in investigating the association of five CAPN10 SNPs (UCSNP-44, UCSNP-43, UCSNP-56, UCSNP-19 and UCSNP-63) with polycystic ovary syndrome among South Indian women." (PMID 22384174, 2012). "Moreover, the CAPN10 gene has been associated with the presence of metabolic syndrome (MS) in T2DM and in polycystic ovary syndrome (PCOS)." (PMID 18698425, 2008). "Cysteine protease Calpain 10 (CAPN10) has been associated with T2DM, hypertension, hypercholesterolemia, increased body mass index (BMI) and polycystic ovary syndrome (PCOS), a reproductive disorder of women in which isunlin resistance seems to play a pathogenic role." (PMID 17227582, 2007).
Hypertension (3 papers, 2007 to 2008). The presence of chronic increased pressure in the systemic arterial system. "Furthermore, CAPN10 has been associated with hypertension and elevated body mass index (BMI) by different groups." (PMID 17227582, 2007).
ovarian carcinoma (3 papers, 2020 to 2024). A malignant neoplasm originating from the surface ovarian epithelium. "In the present study, RPL23, FGFR1OP2, CAPN10, ALDH1L1 and ACSM1 were significantly downregulated in ovarian cancer, while the up-regulation of RPL23, FGFR1OP2, CAPN10 and ALDH1L1 was associated with poor prognosis in patients with ovarian cancer." (PMID 39478854, 2024). "Moreover, miR-142-5p was found downregulated, while CAPN10 was overexpressed in ovarian cancer cells." (PMID 34204094, 2021). "PKM2, MRPS12, NDUFC2, HPDL, MRPL14, COA6 and RNF144B were significantly upregulated in ovarian cancer tissues than in normal tissues (P < 0.05), while RPL23, FGFR1OP2, CAPN10, ALDH1L1 and ACSM1 were significantly down-regulated (P < 0.05)." (PMID 39478854, 2024).
gastric cancer (2 papers, 2014 to 2022). A primary or metastatic malignant neoplasm involving the stomach. "In gastric cancer, the DNA methylation levels of the promoter of CAPN10 became much higher, leading to loss of CTCF binding." (PMID 36333291, 2022). "Inhibition of Calpain-10 in gastric cancer cells by short hairpin RNA or pharmacological inhibitor was found to effectively reduced growth ability and vessel density in vivo." (PMID 25226618, 2014). "Hence, we compared GPR35 and CAPN10 expression fluctuation in kidney and gastric cancer tissues, but also their relationship in kidney cell and gastric cancer cells when knocked out CTCF-bd (binding domain) for CAPN10." (PMID 36333291, 2022). "Herein, we hypothesize that Biseugenol inhibits the EMT progression of gastric cancer cells through a Calpain-10- interaction with AhR and regulated Snail pathway." (PMID 25226618, 2014). "Importantly, using a siRNA to Calpain-10 activity led to a significant abatement of Biseugenol-induced activity in human gastric cancer cells after 1 h treatment." (PMID 25226618, 2014). "Furthermore, compared to kidney cancer (Pan-kidney cohort, KIPAN), ERR event in gastric cancer resulted in a higher ratio between GPR35 and CAPN10." (PMID 36333291, 2022). "We also assessed transfected Calpain-10 siRNA knocks down the co-localization of endogenous Calpain-10/AhR in Biseugenol-treated gastric cancer cells (data not shown)." (PMID 25226618, 2014).
gestational diabetes (2 papers, 2021 to 2024). Carbohydrate intolerance first diagnosed during pregnancy. "The association between TCF7L2 and CAPN10 gene polymorphisms and gestational diabetes mellitus (GDM) has been explored in diverse populations across different geographical regions." (PMID 38166877, 2024). "Recent studies have found that single nucleotide polymorphisms (SNPs) in TCF7L2, CAPN10, KCNQ1, and ADIPOQ are associated with the onset of gestational diabetes." (PMID 38166877, 2024).
limb girdle muscular dystrophy type 2A (2 papers, 2012 to 2013). "Genetic association studies have implicated calpains in disease pathologies including limb-girdle muscular dystrophy type 2A (LGMD2A, CAPN3), susceptibility to type II diabetes (CAPN10) and gastric cancer (CAPN8/9)." (PMID 22479198, 2012).
metabolic syndrome (2 papers, 2008 to 2017). A cluster of metabolic risk factors for CARDIOVASCULAR DISEASES and TYPE 2 DIABETES MELLITUS. "Thus, further in-depth researches will be performed to explore the mechanism of Calpain-10 SNPs on the influencing factors, such as total cholesterol and triglycerides in cardiovascular diseases and metabolism syndromes." (PMID 28422847, 2017).
ampullary cancers (1 paper, 2012). "There is little information in pancreatic, bile duct or ampullary cancers regarding calpain function or activity; however, single nucleotide polymorphisms in calpain-10 (CAPN10) have been associated with pancreatic cancer in smokers." (PMID 23140395, 2012).
bile duct cancer (1 paper, 2012). "The expression of μ-calpain, m-calpain and calpastatin has not been previously examined in pancreatic, ampullary or bile duct cancers, however, a single nucleotide polymorphism of calpain-10 (CAPN10) has been associated with an increased risk of developing pancreatic cancer in smokers." (PMID 23140395, 2012).
breast carcinoma (1 paper, 2021). "The results showed that some of the genes related to the prognosis of breast cancer (IKBKB, ATG16L2, CLN3, MBTPS2, TSC2, and CAPN10) had a higher frequency of mutations." (PMID 34457116, 2021).
cognitive disorder (1 paper, 2018). A disease affects cognitive processes. "Impairment of MAP1B cleavage by abnormal CAPN10 might well cause cognitive disorders, as MAP1B has been shown to coordinate microtubule and actin filament remodeling in neural cells." (PMID 30425305, 2018).
diabetic nephropathy (1 paper, 2023). "Finally, the results of this study provide valuable insights into the potential role of the Calpain 10 SNP 19 genotype in the pathogenesis of diabetic nephropathy." (PMID 38139275, 2023). "Additionally, the clinical relevance of these associations should be further investigated to determine whether they have implications for the diagnosis and management of diabetic nephropathy patients with different Calpain 10 SNP 19 genotypes." (PMID 38139275, 2023). "The lack of significant differences in serum TGF-β, serum IL-17, and serum Mg levels between the genotypes suggests that these biomarkers may not be strongly influenced by the Calpain 10 SNP 19 genotype in diabetic nephropathy patients." (PMID 38139275, 2023).
dyspepsia (1 paper, 2025). An uncomfortable, often painful feeling in the stomach, resulting from impaired digestion. "The SNPs rs2289669 (SLC47A1) and rs3792269 (CAPN10) were significantly associated with greater HbA1c reduction, glycemic goal achievement, and risk of dyspepsia." (PMID 41050568, 2025).
esophageal squamous cell carcinoma (1 paper, 2020). Esophageal squamous cell carcinoma (ESCC) is a type of esophageal carcinoma (EC) that can affect any part of the esophagus, but is usually located in the upper or middle third. "The high expression of CAPN10 suggests a good prognosis for esophageal squamous cell carcinoma, however, the high expression of CAPN10 in this study suggests a poor prognosis for HCC." (PMID 31988807, 2020).
gastric tumor (1 paper, 2014). "Taken together, these findings suggest that the therapeutic activation of Calpain-10 by Biseugenol-treated and further interaction with AhR suppresses both gastric tumor growth and peritoneal dissemination by inducing ER." (PMID 25226618, 2014). "Taken together, these data suggest that Calpain-10 activation and AhR inhibition by Biseugenol impedes both gastric tumor growth and peritoneal dissemination by inducing ER stress and inhibiting EMT." (PMID 25226618, 2014).
hepatocellular carcinoma (1 paper, 2024). A malignant tumor that arises from hepatocytes. "In prediction models for autophagy-related genes, multiple autophagy genes are involved, such as ATG10, ATIC, BIRC5, and CAPN10, and their changes effectively affect the survival time of hepatocellular carcinoma patients." (PMID 39502521, 2024).
Hirsutism (1 paper, 2012). Abnormally increased hair growth referring to a male pattern of body hair (androgenic hair). "Another study in the Spanish population has suggested that CAPN10 UCSNP-43 allele somehow influences the hirsutism score in hyperandrogenic patients while UCSNP-45 could be associated with idiopathic hirsutism." (PMID 22384174, 2012).
Hypercholesterolemia (1 paper, 2007). An increased concentration of cholesterol in the blood. "A reanalysis of CAPN10 gene in a larger PCOS population, allowed us to identify specific haplotypes associated with hypercholesterolemia in PCOS patients." (PMID 17227582, 2007).
Intellectual disability (1 paper, 2018). "More recently, it was reported that homozygous mutations of CAPN10, an in frame insertion of five amino acids in the calpain catalytic domain and two kinds of nonsense mutation, were identified in patients with intellectual disability including cognitive disorders." (PMID 30425305, 2018).
ischemic stroke (1 paper, 2017). A stroke disorder caused by obstruction of blood flow to the brain, due to thrombotic (local blood clot formation) or embolic (due to a blood clot or other material traveling from another site) event. "The purpose of this study is to elucidate correlation between Calpain-10 single-nucleotide polymorphisms (SNPs) and the incidence of OSAHS followed by ischemic stroke (IS)." (PMID 28422847, 2017).
laryngeal carcinoma (1 paper, 2021). Carcinoma that arises from the laryngeal epithelium. "This suggests that EGFR and INHBA can serve as prognostic hub genes for laryngeal cancer collectively with pRS genes (CFLAR, DAPK2, TSC2, CAPN10, MBTPS2, PEX14, FADD and ST13)." (PMID 34093817, 2021).
leukoaraiosis (1 paper, 2009). "Region 5, which illustrates univariate associations between the SNPs and leukoaraiosis, shows that four SNPs have significant, replicated and cross-validated associations (F3_rs3917643, CAPN10_rs7571442, MMP2_rs9928731, KITLG_rs995029)." (PMID 19351393, 2009).
melanoma (1 paper, 2025). A malignant, usually aggressive tumor composed of atypical, neoplastic melanocytes. "Honokiol inhibits the oncogenic KRT18 protein in melanoma and prevents recurrence of advanced melanoma using the β-catenin/MITF axis via prompt calpain-10 and CCAAT homologous protein (CHOP/GADD153) regulated cascades." (PMID 40943669, 2025).
cancer (5 papers, 2014 to 2023). A tumor composed of atypical neoplastic, often pleomorphic cells that invade other tissues. "The animal model study also revealed that inhibition/inactivation of AhR or Biseugenol-induced Calpain-10-activation suppressed the growth of tumor mass and reduced the frequency of peritoneally disseminated cancer cells." (PMID 37830596, 2023). "The survival plots and HR values suggested that GPR35 is a promote cancer gene, nevertheless, CAPN10 is a suppressor cancer gene in GC." (PMID 36333291, 2022). "Biseugenol activated Calpain-10-mediated cleavage of AhR in the cancer cells." (PMID 37830596, 2023). "Hence, we will perform animal experiments in the near future to validate the KCNQ1OT1/MIR‐142‐5p/CAPN10 axis in OC and to confirm their roles in regulating cancer progression." (PMID 31909901, 2020). "However, to our knowledge, nothing is known about the protein expression or cellular function of calpain 10 or the cellular and molecular mechanisms related to ER stress in the development, progression, and metastasis of cancer still remain to be clarified." (PMID 25226618, 2014). "Transfection cancer cells with siRNA-Calpain-10, but not scramble siRNA (data not shown), caused reversion of AhR down-regulation." (PMID 25226618, 2014). "Taken together, targeting Calpain-10 may help eliminate AhR, thereby preventing cancer progression." (PMID 25226618, 2014).
cardiovascular disease (4 papers, 2007 to 2017). "As its homologue CAPN10, CAPN5 seems to influence traits related to increased risk for cardiovascular diseases." (PMID 17227582, 2007).
tumor (4 papers, 2014 to 2023). "Notably, 8 autophagy-related genes (CAPN10, DAPK2, MBTPS2, ST13, CFLAR, FADD, PEX14 and TSC2) and 2 immune cells (Mast cells and Eosinophils) were revealed to be highly associated with tumor prognosis." (PMID 34093817, 2021). "Our data demonstrated that suppression of AhR by shRNA-AhR or exposure Biseugenol-induced Calpain-10-activity could reduce tumor growth or peritoneal dissemination in tumor tissues." (PMID 25226618, 2014).
metabolic disease (2 papers, 2008 to 2025). A congenital disorder (due to inherited enzyme abnormality) or acquired (due to failure of a metabolically important organ) disorder resulting from an abnormal metabolic process. "Together, these findings reinforce that both metformin pharmacokinetics (via SLC47A1) and pharmacodynamics (via CAPN10) are subject to genetic regulation, supporting genotype-guided therapy in metabolic disease." (PMID 41050568, 2025).
hematological malignancies (1 paper, 2021). "CAPN10 plays important roles in the translocation of glucose transporter 4 (GLUT4), secretion of insulin and apoptotic processes in pancreatic cells, while TSPAN8 has been described as a prognostic indicator for patients with certain solid tumors, but not for hematological malignancies." (PMID 34502231, 2021).
CAPN10 also shares sentences with these, for which no sentence is quoted: asthma (2 papers); atherosclerosis (2); Glucose intolerance (2); age-related macular degeneration (1); behavioral disorders (1); brachydactyly (1); colon tumor (1); coronary artery disease (1); dyslipidaemia (1); fat (1); Hirschsprung disease (1); Hyperglycemia (1); kidney cancer (1); metabolism (1); muscular dystrophy (1); pancreatic cancer (1); prostate carcinoma (1); renal carcinoma (1); ulcerative colitis (1); vitiligo (1).